ADCY4 (adenylate cyclase 4)
Description:
Catalyzes the formation of the signaling molecule cAMP in response to G protein signaling.
Synonyms: AC4
Tractability: Antibody: UniProt places it where antibodies can reach, with high confidence; its Gene Ontology location is reachable by antibodies, with high confidence; UniProt predicts a signal peptide or a membrane-spanning region. PROTAC: ubiquitination databases record sites on it; a small molecule that binds it is known.
Gene: Protein-coding gene on chromosome 14 (24,318,349 to 24,335,093, reverse strand). Ensembl gene ENSG00000129467.
Subcellular location: Cell membrane; Cytoplasm
Subcellular location (Human Protein Atlas): Mitochondria; Nucleoplasm; Plasma membrane
Pathways (Reactome):
Signal Transduction: Adenylate cyclase activating pathway; G alpha (i) signalling events; G alpha (s) signalling events; G alpha (z) signalling events; GPER1 signaling; Hedgehog 'off' state; PKA activation
Disease: ADORA2B mediated anti-inflammatory cytokines production; FCGR3A-mediated IL10 synthesis
Metabolism: Glucagon signaling in metabolic regulation; PKA activation in glucagon signalling
Cellular responses to stimuli: High laminar flow shear stress activates signaling by PIEZO1 and PECAM1:CDH5:KDR in endothelial cells
Neuronal System: Adenylate cyclase inhibitory pathway
Transport of small molecules: Vasopressin regulates renal water homeostasis via Aquaporins
Gene Ontology:
Molecular function: protein binding; protein kinase C binding; adenylate cyclase activity; phosphorus-oxygen lyase activity
Biological process: adenylate cyclase-activating G protein-coupled receptor signaling pathway; adenylate cyclase-modulating G protein-coupled receptor signaling pathway; cAMP biosynthetic process; cellular response to glucagon stimulus; renal water homeostasis; vascular endothelial cell response to laminar fluid shear stress; cyclic nucleotide biosynthetic process; intracellular signal transduction
Cellular component: cytoplasm; plasma membrane; membrane; dendrite
Genetic constraint (gnomAD): Loss-of-function variants: 111 observed, 119.32 expected, observed/expected ratio (o/e) 0.93, 90% interval 0.8 to 1.09. The upper end of that interval is the gene's LOEUF score, 1.09, which puts it in group 4 of 6, group 1 being the genes least tolerant of losing a copy. Missense variants: 1,256 observed, 1,330.9 expected, observed/expected ratio (o/e) 0.94, 90% interval 0.9 to 0.99. Synonymous variants: 576 observed, 562.83 expected, observed/expected ratio (o/e) 1.02, 90% interval 0.95 to 1.1.
Homologues: Orthologues: chimpanzee ADCY4 (99% identical), macaque ADCY4 (99% identical), dog ADCY4 (94% identical), pig ADCY4 (94% identical), rabbit ADCY4 (94% identical), guinea pig ADCY4 (92% identical), mouse Adcy4 (92% identical), rat Adcy4 (92% identical), tropical clawed frog adcy4 (61% identical). Paralogues in human: ADCY2 (56% identical), ADCY7 (52% identical), ADCY6 (37% identical), ADCY1 (36% identical), ADCY5 (36% identical), ADCY8 (35% identical), ADCY3 (33% identical), ADCY9 (27% identical), GUCY2F (16% identical), NPR1 (16% identical), GUCY2D (15% identical), NPR2 (15% identical), and 5 more.
Diseases named in the same sentence as ADCY4 in open-access papers:
ADCY4 is named in the same sentence as 31 diseases in open-access papers, as found by Europe PMC text mining. Sharing a sentence is not in itself a finding about the gene and the disease. The quoted sentences say what the papers report.
breast carcinoma (8 papers, 2020 to 2022). "Methylation pattern of MAST1, PRDM14, and ZNF177 may represent new diagnostic biomarkers for breast cancer, while methylation of ADCY4, CPXM1, DNM3, PRDM14, PRKCB, and ZNF177 may hold prognostic potential for breast cancer." (PMID 33499882, 2021). "ADCY4 mRNA expression is significantly downregulated in breast cancer compared to the normal tissues, while the level more than triples in invasive breast cancer." (PMID 35832555, 2022). "ADCY4 expression levels have been correlated with overall survival in some cancers, such as breast cancer and in lung adenocarcinoma." (PMID 35328227, 2022). "The results for seven candidate genes—CCDC181, GCM2, ITPRIPL1, ENPP2, LOC643719, ZNF177 and ADCY4—were successfully validated by sequencing and stable detection in ccfDNA from the plasma of Taiwanese patients with breast cancer." (PMID 33803633, 2021). "The methylation patterns of the CCDC181, GCM2, ITPRIPL1, ENPP2, LOC643719, ZNF177 and ADCY4 genes were further determined in plasma samples from healthy and early breast cancer patients." (PMID 33803633, 2021). "Aberrant methylation patterns of the CCDC181, GCM2, ITPRIPL1, ENPP2, LOC643719, ZNF177 and ADCY4 genes were identified and further evaluated in paired tumor and normal tissues of breast cancer patients." (PMID 33803633, 2021). "Aberrant methylation of CCDC181, GCM2, ITPRIPL1, ENPP2, LOC643719, ZNF177 and ADCY4 was found in breast cancer patients from the Taiwanese and TCGA cohorts using the methylation array." (PMID 33803633, 2021). "illustrated that ADCY4 was obviously downregulated in primary breast cancer (P<1.00e-12) compared to normal tissues, and this downregulation was closely correlated with ADCY4 promoter hypermethylation." (PMID 34178627, 2021). "Thus, ADCY4 is a potential biomarker and therapeutic target to predict the prognosis of human breast cancer." (PMID 35832555, 2022). "Our findings of gene expression and breast cancer prognosis were consistent with the previous evidence for HSP90AA1, ADCY4, and GNG7." (PMID 35729536, 2022). "As expected, methylation levels of ADCY4, CPXM1, DNM3, GNG4, MAST1, PRDM14, and ZNF177 were found to be increased in breast cancer, and all with p values lower than 0.001." (PMID 33499882, 2021). "However, poorer sensitivity or specificity in plasma for the early detection of breast cancer was found for the LOC643719, ENPP2, ADCY4 and RASSF1 genes." (PMID 33803633, 2021). "Methylated ENPP2 and ADCY4 were found in most healthy and breast cancer patients, indicating that they are not specific biomarkers for breast cancer patients." (PMID 33803633, 2021). "To further determine the methylation pattern of breast cancer tissues in the Taiwanese cohort, we analyzed the methylation levels of CCDC181, GCM2, ITPRIPL1, ENPP2, LOC643719, ZNF177 and ADCY4 in tumors and adjacent normal tissue in Taiwanese breast cancer patients." (PMID 33803633, 2021). "To further explore the clinical value of these biomarkers, we evaluated whether 6 of our differentially methylated genes—ADCY4, CPXM1, DNM3, PRDM14, PRKCB, and ZNF177—had any relation with overall survival of breast cancer patients." (PMID 33499882, 2021). "Unlike gastric cancer, ADCY4 may impose a tumor inhibitory effect in breast cancer, although this effect is terminated by the gene silencing caused by DNA methylation." (PMID 35832555, 2022). "Moreover, we showed that DNA methylation landscape of ADCY4, CPXM1, DNM3, PRDM14, PRKCB, and ZNF177 could be selected as accurate biomarkers for the prognosis of breast cancer." (PMID 33499882, 2021).
type 2 diabetes (2 papers, 2016 to 2020). "Additionally, there was a strong upregulation of several K+ channel genes in Aldh1b1tm1lacZ null islets, including Kcnj11, a type 2 diabetes risk factor, and expression of adenylate cyclases Adcy4 and Adcy5 was repressed." (PMID 26518685, 2016).
Cognitive impairment (1 paper, 2019). Abnormal cognition is characterized by deficits in thinking, reasoning, or remembering. "Among the significantly enriched signaling pathways from KEGG analysis, oxytocin signaling pathway (PATH:04921; Cacng2, Adcy1, Kcnj4, Kcnj9, Adcy8, Pik3cd, Elk1, Adcy4, Camkk2, Cacng7, Nos3, Kcnj2) may play an important role in the sevoflurane-induced cognitive impairment." (PMID 31582589, 2019).
colon cancer (1 paper, 2025). "Silencing adenylate cyclase 4 (ADCY4) could reduce the stability of ALOX12B and inhibit its overexpression, which indicates that ADCY4 is crucial for maintaining the expression and stability of ALOX12B, essential for the effective execution of ferroptosis in colon cancer cells treated with solanine." (PMID 41471274, 2025).
degenerative myopia (1 paper, 2025). "Among these findings, genes such as ADCY4, a regulator of the cAMP pathway, were functionally linked to high myopia, while THBS1, involved in collagen degradation, was closely associated with the pathophysiology of degenerative myopia." (PMID 40110040, 2025).
hemoglobinopathy (1 paper, 2022). "The expression gene analysis showed that PTGFR (downregulated) and GPR56 (upregulated) are differentially expressed in placentas of women with sickle cell anemia as well as SPOCK1 (downregulated) and ADCY4 (upregulated) in placentas of women with hemoglobinopathy HbSC." (PMID 36129958, 2022). "Thereby, due to the increased ADCY4 expression in placentas from third trimester (HbSC group), we suggest that biological processes involved ADCY4 could be increased in this gestational age, impairing the placenta development in women with SC hemoglobinopathy." (PMID 36129958, 2022).
Hyperglycemia (1 paper, 2024). An increased concentration of glucose in the blood. "Downregulation of ADCY4 has been associated to impaired mitochondrial function in murine hearts, while hyperglycemia-induced cardiac hypertrophy and apoptosis act through endoplasmic reticulum stress-JNK3 signaling pathway." (PMID 38904047, 2024).
myopia (1 paper, 2025). "Therefore, it’s reasonable to speculate that ADCY4, as cAMP regulator is functionally associated with high myopia." (PMID 40110040, 2025).
cancer (8 papers, 2017 to 2025). A tumor composed of atypical neoplastic, often pleomorphic cells that invade other tissues. "In comparison to normal tissues, Nos2, Hgf, Lama1, Csf3r, Csf2rb2, Col4a1, Col4a2, Adcy2, Adcy4, Gstm3 and Gstm6 were identified as the most significant genes in cancer pathways." (PMID 37774039, 2023). "Several studies have reported that ADCY4 showed lower expression in various cancer tissues compared to normal tissues." (PMID 34178627, 2021). "Signal transduction genes (i.e., ADCY4/7/8/9,) are also in the list of our 102 genes, which also includes cancer stem cell signaling genes (i.e., WNT7A, GLI1/2/3, NOTCH2/3/4, ALDH1A3)." (PMID 29304754, 2018). "To validate these results, based on the 340 epigenetically silenced genes in at least five cancer types, we drew a protein-protein interaction network and found some genes with higher degrees of interaction, such as ADCY4, ADCY8, and PRKCB.." (PMID 28060724, 2017). "In fact, few studies have reported the role of ADCY4 in cancer." (PMID 34178627, 2021). "By contrast, ADCY1 expression did not affect the prognosis of AML patients, suggesting the actions of group 2 adenylyl cyclases (ADCY2, ADCY4 and ADCY7) in AML differ from those in other cancers." (PMID 32568101, 2020). "For example, AGTR1, GRIN2A, ITPKB, and SLC8A3 were repressed by hypermethylation in six cancer types, and ADCY4, ADCY8, BST1, and PRKCB were inhibited by hypermethylation in five cancer types." (PMID 28060724, 2017).
ADCY4 also shares sentences with these, for which no sentence is quoted: infection (8 papers); virus infection (7); tumor (3); Age-Related Hearing Loss (1); asthma (1); cervical cancer (1); diabetic kidney disease (1); diabetic retinopathy (1); glioma (1); hypertrophy (1); lung adenocarcinoma (1); Lung Squamous Cell Carcinoma (1); multiple sclerosis (1); neuroblastoma (1); neuropathy (1); osteosarcoma (1); prostate carcinoma (1); psychiatric disorder (1); sickle cell anemia (1); stress-related disorder (1); Stroke (1); uveitis (1).